BCL2 (BCL2 apoptosis regulator)
Diseases named in the same sentence as BCL2 in open-access papers (continued):
Sharing a sentence is not in itself a finding about the gene and the disease.
tumor (continued). "Additionally, HMCLPs can initiate apoptosis signaling pathways, such as the Bax/Bcl-2 pathways, by causing oxidative damage to cellular lipids, proteins, and DNA, ultimately inducing tumor cell death." (PMID 39513925, 2024). "STAT3-associated downstream proteins including CyclinD1, Bcl-2, and Bax could control multiple processes essential for the progression of cancer, such as tumor formation, growth, cell death, and differentiation." (PMID 39153914, 2024). "Interestingly, we found several tumor-specific TMD mutations in the COSMIC database (cancer.sanger.ac.uk/cosmic) underpinning the impact of Bcl-2 TMDs on the apoptosis signaling network by affecting localization, interaction or “double-bolt lock” mechanism." (PMID 39048751, 2024). "However, mutations in the Bcl-2 gene or the upregulation of other anti-apoptotic genes to compensate can lead to chemoresistance and promote tumor growth and cell survival." (PMID 38612619, 2024). "However, in tumor cells, high expression of Bcl-2 is often associated with increased anti-apoptotic ability and increased drug resistance of tumor cells." (PMID 39605083, 2024). "Immunohistochemical staining of thymus tissue sections showed that SNLP‐1a could restore their normal Bcl‐2/Bax ratio and reduce the damage caused by tumor invasion." (PMID 39155844, 2024). "Scientific evidence indicated that vitamin D intensified the effects of paclitaxel through down-regulated B-cell lymphoma-2 (Bcl-2) expression and upregulated the expression of Bcl-2 associated X (Bax) and cleaved caspase-3 in BC cells, thereby promoting the apoptosis of BC tumor cells." (PMID 39806750, 2024). "The Bcl-2 gene is associated with tumor occurrence, development, and prognosis." (PMID 38167446, 2024). "One of the most important factors that may contribute to a tumor’s susceptibility to BCL-2 inhibition is the level of BCL-2 expression that is inherent to the tissue and its survival." (PMID 39906657, 2024). "Since IL-8 is able to inhibit not only apoptosis-inducing proteins caspase 3 and 9, but also PARP, and promotes the expression of Bcl-2, Survivin or Bcl-xl, -xs; tumor-associated enhanced IL-8 may directly counteract apoptosis and ICI therapy response." (PMID 38891846, 2024). "Given VTC is very selective for BCL-2, one of the most important factors that may contribute to a tumor’s susceptibility to BCL-2 inhibition is the level of BCL2 expression that is inherent to the tissue and its survival." (PMID 39906657, 2024). "Moreover, it has been reported that Bcl-2 expression is associated with tumor progression and development of androgen-independent prostate cancer." (PMID 37241040, 2023). "However, these all lncRNAs cause increased expression level of Bcl-2, inhibition of apoptosis, and tumor progression ultimately." (PMID 37313458, 2023). "Another investigation evaluated the significance of mortalin, Bcl-2, and Bax as prognostic factors in iCCA, and found that an increased level of Bcl-2 and mortalin and the down-regulation of Bax were linked to anti-apoptotic effects and tumor progression in iCCA." (PMID 37509299, 2023). "To investigate the underlying mechanism, we evaluated several tumor growth and migration markers by western blot, specifically Bcl-2 and p21, modulators of apoptosis and cancer progression, respectively, and metalloproteinase-2 (MMP2) and -9 (MMP9), related with tumor invasion ability." (PMID 36800968, 2023). "Cepharanthine is known to induce reactive oxygen species production to achieve anti-tumor effects in myeloma cells and mouse lymphoma cells, causing upregulation of p21Waf1/Cip1 and Bax, and downregulation of cyclin A and Bcl-2." (PMID 37446681, 2023).
tumor (continued). "Although we did not observe an apparent morphological and histopathological difference in spleen, lymph node and bone marrow in both strains, the loss of Tfl might affect tumor progression in Bcl2-Tg/Tfl-/- mice." (PMID 37304286, 2023). "Furthermore, Ki-67 has also been implicated in tumor proliferation and invasion along with other markers like Bcl2." (PMID 37313057, 2023). "Moreover, a low-dose of naltrexone upregulated the expressions of the opioid growth factor receptor and apoptotic factors (PARP, caspases 3 and 9, Bax) and downregulated the expressions of Ki67 and Bcl-2, causing apoptosis in tumor cells." (PMID 37509632, 2023). "In various cancers, increased expression of BCL-2 protein is associated with enhanced drug resistance of tumor cells, although in some cases, its expression may be lower in tumor tissues compared to the surrounding normal tissues." (PMID 38099288, 2023). "In addition, AUF1 can trigger an anti-tumor response by destabilizing mRNAs encoding the anti-apoptotic protein BCL2 and the pro-inflammatory factors GM-CS, IL-6, IL-10, and TNF-α." (PMID 37631029, 2023). "Furthermore, WFEA significantly increased the protein expression of apoptosis-related Caspase3, inhibited the protein expression levels of MMP3 (associated with tumor invasion and metastasis) and apoptosis-inhibiting gene Bcl2." (PMID 36949111, 2023). "Interestingly, the combination also caused a significant decrease in BCL-2 protein levels in these tumor samples." (PMID 36588105, 2023). "Bcl-2 is closely associated with invasion and migration of tumor cells." (PMID 34980181, 2022). "Mir-21 acts as an oncogene and is able to modulate tumorigenesis through regulation of the Bcl-2 gene, showing that Bcl-2 up-regulation may be caused by miR-21 over-expression preventing tumor-cell apoptosis." (PMID 35216464, 2022). "Finally, DORZOLAMIDE has shown antitumor activity which affects TXNIP-dependent tumour suppression pathways and also causes downregulation in the level of bcl-2 in cancer cells." (PMID 35379165, 2022). "Thus, by decreasing Bcl-2 expression simultaneously with increasing Bax and Bad gene expression, HPex increases the susceptibility of tumor cells to the process of apoptosis." (PMID 35050083, 2022). "Furthermore, the changes in apoptosis-related proteins and cell cycle-associated proteins, including PUMA, Bcl-2, Bax, Caspase-9, p21, and Cyclin D1, in the tumor tissues were consistent with the in vitro results." (PMID 35759135, 2022). "Bcl-2 is a positive regulator of apoptosis, which is associated with anti-tumor immunity." (PMID 35126391, 2022). "ALK TKIs also cause adaptive changes in tumor cells that favor their survival such as the upregulation of Bcl-2 and inhibition of autophagy; therapeutic strategies that target these changes may be effective in the treatment of ALK+ ALCL." (PMID 35211406, 2022). "Regarding CNAs, the main affected genes in this series of primary MN that recurred are located on chromosomes 22q (TIMP3), 1p (TP73), 6q (ESR1 and PARK2), and 18q (BCL2); the association among these chromosomes’ alterations and tumor recurrence has been previously demonstrated." (PMID 36011000, 2022). "Similarly, one of the mechanisms underlying resistance to the anti-tumor antibiotic doxorubicin is the abnormal increase in the anti-apoptotic protein BCL-2." (PMID 36365147, 2022). "In the analysis for OS, all four scales selected for further analysis had prognostic value for OS after adjusting for IPI alone, and after adjusting for IPI and other key variables (cell of origin, BCL2 mutation status, and total metabolic tumor volume) in addition to IPI." (PMID 35322932, 2022).
tumor (continued). "Tumor cells can acquire resistance to apoptosis by downregulation or mutation of proapoptotic proteins such as BCL2 associated X (BAX) or by the expression of anti-apoptotic proteins like B-cell lymphoma 2 (BCL2)." (PMID 34268250, 2021). "Due to the neutralization of a broad spectrum of proapoptotic Bcl-2 proteins, Mcl-1 may compensate for the loss of other antiapoptotic Bcl-2 proteins in tumor cells, suggesting it as a potential key regulator of antiapoptotic control in cancer cells." (PMID 34028599, 2021). "Although the overexpression of Bcl-2 predisposes to tumour invasiveness, some studies have reported that it may represent a crucial target for Bcl-2 inhibitors and, therefore, a good prognostic factor in patients with different types of cancer." (PMID 34439105, 2021). "Through the review of the published studies, we discovered the role of ARID1A alterations or expression loss in the regulation of Bcl-2 expression and apoptosis of tumor cells which might participate into the resistance to EGFR-TKIs." (PMID 34715776, 2021). "The increased expression of Bcl-2 is linked with advanced-stage neoplasms and poor differentiation." (PMID 34638779, 2021). "BIM encodes a BH3-only protein crucial for BCL-2-induced apoptosis of tumor cells." (PMID 34722761, 2021). "Furthermore, it is known that BCL-2 overexpression is associated with an aggressive tumor phenotype and poor survival." (PMID 34063475, 2021). "As up-regulation of Mcl-1 and Bcl-2 is associated with proliferation and survival of the tumor cells; we therefore sought to assess whether miRNA-15a could inhibited the proliferation of CLL cells." (PMID 34319043, 2021). "Furthermore, the enhanced expression and activation of Notch1 was associated with a passage-dependent increase of Bcl-2 levels and downregulation of p21, thus promoting survival and cell cycle progression of tumor spheres." (PMID 33922104, 2021). "In contrast, miR-503 expression has been reported to be upregulated in certain cancers and identified as a tumor-associated miRNA that directly targets Bcl2 apoptosis regulator to promote apoptosis of dendritic cells, indicating a mechanism for tumor immunotolerance." (PMID 34222229, 2021). "CREB may be less potent than PAK4 because the role of CREB is more restricted compared with PAK4, but it may specifically enhance the expression of Bcl‐2 with a reduced risk of tumour formation." (PMID 33615605, 2021). "Tumor size, lymph node involvement, and Bax/Bcl-2 ratio were also higher in advance-stage tumors in our study, which may suggest that Bax/Bcl-2 ratio levels are associated with OSCC aggressiveness." (PMID 32901694, 2020).
tumor (continued). "Analysis of pharmacodynamic markers within harvested PTEN-deficient tumour samples similarly indicated IR to induce the expression of Bcl-2, a known mediator of RT resistance in a number of cancer models, but that this was attenuated by inhibition of CXCR1/CXCR2 signalling." (PMID 32743555, 2020). "Notably, increased Bcl-2 expression has been implicated in tumor progression, and the induction of chemoresistance in cancer models, as well as correlated with poor prognosis in cancer patients." (PMID 32717779, 2020). "Thus, the objective of our study is to evaluate the histopathological features of CRC, and to investigate the association of Bcl-2 expression with prognostic parameters like tumor type, stage and grade." (PMID 31754362, 2019). "In the 57 luminal FMCs, Bcl-2 positivity was also associated with better outcome in terms of disease-free interval, overall survival and specific survival, independently of the pathologic tumor size and tumor-associated inflammation." (PMID 30630524, 2019). "Moreover, mice implanted with B16F10 cells and treated with 100 mg/kg and 4 Gy IR for 2 weeks, underwent an inhibition of tumor growth caused by a down-regulation of Bcl-2 and Survivin, proved by western blot analysis of the tumor tissue." (PMID 31652849, 2019). "The underlying molecular mechanisms may be associated with the induction of tumor cell apoptosis by inhibition of the STAT3/Bcl-2 signal pathway." (PMID 31777595, 2019). "Of note, PD-L1i was marginally associated with Bcl-2 expression in tumor cells (p = 0.051)." (PMID 30458835, 2018). "The intrinsic mechanism of cancer cell may influence anti-tumor immunity, where Bcl-2 protein may act as a tumor-associated antigen, although further studies are required for support." (PMID 30458835, 2018). "Moreover, in mice xenografts from patient-derived BCLC9 cells, better tumor response to sorafenib was associated to higher changes in the BCL-2 mRNA pattern." (PMID 29682179, 2018). "At this stage, we could not thoroughly address the roles of AUF1 and TTP in modulating apoptosis and growth of cancer cells, it appears that AUF1 and TTP are implicated in the modulation of tumor growth by regulating Bcl‐2 expression even at basal level." (PMID 30524947, 2018). "Additionally, improved tumour cell survival and increased BCL-2 expression linked decreased RGS2 levels to fundamental tumour advantages." (PMID 30467386, 2018). "Bcl-2 protein is the critical component of tumor associated apoptosis event." (PMID 29229973, 2017). "Since, activated STAT3 protects tumor cells from apoptosis and promote cell growth by regulating multiple genes associated with cell proliferation and anti-apoptotic proteins such as surviving cyclin D1,c-Myc, Fas, Mcl-1, Bcl-xL, and Bcl-2." (PMID 29254150, 2017). "We next explored the potential mechanism underlying the anti-tumor activity of Cu(sal)(phen) in vivo by examining the expression levels of the apoptotic proteins Bcl-2, Bcl-xL, survivin and proliferation marker Ki-67 by immunohistochemical staining of the tumors and semi-quantitative image analysis." (PMID 28415735, 2017). "BRCA1 expression tended to be lower in older age and in patient with positive family history however, the associations (with basal markers, tumor grade, AR, hormone receptors, bcl2 and Ki67 index) persisted after adjusting for age at diagnosis and family history." (PMID 28863181, 2017). "In particular, BCL-2 up-regulation may be caused by miR-21 over-expression, so preventing the tumor-cell apoptosis that would otherwise be induced by chemotherapy drugs." (PMID 27144561, 2016).
tumor (continued). "Correspondingly, Bcl-2 expression was shown to have a beneficial influence on prognosis, whereas loss of Bcl-2 was found in 70 % of the aggressive triple-negative BC, and was significantly associated with high proliferation, tumor progression, increased risk of death and recurrence." (PMID 27538498, 2016). "Western blot analysis of tumor lysates (derived from L3.6pL cells as xenografts) also showed that the loss of Sp TFs resulted in decreased expression of Sp-regulated gene products, survivin, bcl-2 and EGFR and also decreased expression of Sp TFs." (PMID 26967243, 2016). "Bcl-2 (18q21.33) encodes a protein that is an inhibitor of apoptosis in the cell growth cycle, prevents the normal cell death, and leads to uncontrolled cell growth and tumor development." (PMID 26858789, 2016). "Bcl-2 expression was lost in 70 % of the most aggressive triple-negative BC cases, i.e. those lacking ERα, PgR and Her-2, and was significantly associated with high proliferation, tumor progression and increased risk of death and recurrence." (PMID 27538498, 2016). "Fifty-nine out of 136 patients were available for the retrospective study to examine the possibility that E6, miR-184, Bcl-2, or both combinations may be associated with the tumor response to cisplatin-based chemotherapy in NSCLC." (PMID 27083050, 2016). "Several studies have demonstrated that Bcl-2 is tightly associated with tumor development and progression, and thus may be an underlying molecular biomarker." (PMID 26956728, 2016). "As others reported, Bcl-2 expression was positively correlated with ER and PR expression, but negatively correlated with HER2 expression, grade, and tumor size, confirming Bcl-2’s association with favorable prognostic factors or differentiated markers in both groups with and without tamoxifen." (PMID 26472348, 2015). "In addition, PCNA and Bcl-2 expression have been reported to be closely associated with tumor progression and poor overall survival in PCa." (PMID 26622816, 2015). "The tumor tissue was fixed with 10% formaldehyde solution and the levels of the apoptotic proteins, B-cell lymphoma protein-2 (Bcl-2), Bcl-2-associated X protein (Bax) and pro-angiogenic vascular endothelial growth factor (VEGF), were measured by immunohistochemistry." (PMID 25624914, 2015). "In addition, overexpression of Bcl-2 alone in tumor-associated endothelial cells was sufficient to promote tumor metastasis in a SCID mouse model." (PMID 26509633, 2015). "Furthermore, rutin can cause tumor cell apoptosis through a decrease in Bcl2 expression and the Bax/Bcl2 ratio." (PMID 26062544, 2015). "The expression levels of CDX2, survivin, B-cell lymphoma 2 (Bcl-2), Bcl-2-associated X protein (Bax), cyclin D1, s-phase kinase-associated protein 2 (Skp2) and c-Myc in the tumor cells were analyzed by western blotting and semi-quantitative reverse transcription polymerase chain reaction." (PMID 25738600, 2015). "We next investigated whether TQ-inhibited tumor growth in mice was associated with inactivation of the Notch pathway and expression of p21 and Bcl-2, as in cultured cells." (PMID 26416455, 2015). "In addition vitexin also showed anti-tumor and anti-metastatic activities and they were associated through a proapoptotic process, which is mediated by a decreased Bcl-2/Bax ratio and activation of caspases." (PMID 26121396, 2015). "Our CEC results suggest that Bcl-2 positive tumor-associated endothelial cells may be released from the primary tumors in circulation." (PMID 26509633, 2015). "Hence, it is important to note that BCL-2 is oncogenic and BCL-2 inhibitors experimentally reduce tumour growth, yet BCL-2 expression is associated with a favourable prognosis in MC due to its association with the ER+ subtype." (PMID 25266665, 2014). "While a direct involvement of the cancer-related oncogenes ALK in 2p23.2, MLLT3 in 9p21.3, and BCL2 in 18q21.33 could be excluded, loss of two tumor suppresser gene loci in 9p21 and in 13q14 was found." (PMID 25374696, 2014).